MGMT (O-6-methylguanine-DNA methyltransferase)
Diseases named in the same sentence as MGMT in open-access papers (continued):
Sharing a sentence is not in itself a finding about the gene and the disease.
brain tumors (continued). "In conclusion, we demonstrated that compared to CRT alone, the addition of a single dose IV AMON combined with CRT significantly enhanced CRT efficacy in an MGMT expressing xenograft brain tumor model." (PMID 33850305, 2022). "In this work, we report a sandwich biosensor for the detection of the ds-methylated MGMT gene, a potential biomarker for brain tumors and breast cancer." (PMID 35200358, 2022). "Of these, DSF/Cu was approximately five times more potent than DSF in inhibiting MGMT activity in cultured brain tumor cells." (PMID 36091753, 2022). "We provide proof of concept for the use of non-ablative radiation to guide and enhance the delivery of morpholino oligonucleotides into brain tumor xenograft models to reduce MGMT levels and improve CRT efficacy." (PMID 33850305, 2022). "O6-methylguanine-DNA methyltransferase (MGMT) is a DNA repair protein and chemotherapeutic target that is highly expressed in approximately 80% of brain tumors and other cancers." (PMID 36091753, 2022). "Overexpression of O6-methylguanine DNA methyltransferase (MGMT) contributes to resistance to chemo-radiation therapy (CRT) in brain tumors." (PMID 33850305, 2022). "The 2016 WHO classification of diffuse LGGs heavily weighs molecular mutations classifying primary brain tumors with particular importance assigned to IDH mutation, 1p/19q co-deletion, ATRX mutation, TERT mutations, and MGMT methylation." (PMID 32111869, 2020). "MGMT is highly, and heterogeneously expressed in medulloblastoma, the most common malignant brain tumour in children: MGMT activity varied > 100-fold." (PMID 35582280, 2019). "Many studies have been conducted on MGMT methylation status in various brain tumors, and a direct correlation was observed between methylation of MGMT promoter and tumor type and/or malignancy grade." (PMID 28346397, 2017). "The SVM-based classification of texture patterns is a very promising approach for providing a prediction of the MGMT methylation status of the brain tumors." (PMID 27277032, 2016). "Nevertheless, most primary brain tumors express O6-methylguanine-DNA methyltransferase (MGMT), a cytoprotective DNA repair protein that efficiently reverses the cytotoxic effects of alkylating agents, contributing with tumor resistance." (PMID 23533755, 2013). "Recently, aberrant methylation of MLH1, MGMT and MSI were shown to be associated with mutations in genes such as BRAF, RAS and IDH1 in colon and brain tumours." (PMID 23414134, 2013). "Although multiple preliminary lines of evidence suggest enhanced clinical response rates with dose-intense regimens, there are no published studies to date documenting the effect of these temozolomide schedules on MGMT activity in brain tumour." (PMID 20628383, 2010). "To date, however, there are no studies evaluating the effect of dose-intense temozolomide schedules on MGMT activity in brain tumours." (PMID 20628383, 2010). "Notably, re-expression of wild-type, but not C223S mutant, USP7 restored MGMT protein levels in USP7-depleted T98G cells, linking USP7 catalytic activity to MGMT stabilization in brain tumor cells." (PMID 40835840, 2025). "Because our GBM cell lines including the U251 cells used in our orthotopic brain tumor experiments have low or undetectable MGMT expression, we chose to test effects of imipridones on MGMT expression when used alone or in combination with TMZ in treatment of DIPG cells." (PMID 40145650, 2025). "In future work, the MDL-CA framework will be extended to support multi-class classification, enabling the identification of clinically relevant brain tumor subtypes, such as IDH mutation status or MGMT promoter methylation, which are essential for personalized treatment planning." (PMID 41561860, 2025).
brain tumors (continued). "Our previous findings that hGTX can modulate GSH metabolism, increase protein glutathionylation, and augment oxidative stress in human tumors (unpublished) led to the current study investigating the inhibitory effects of stabilized glutathione mimetic on MGMT in brain tumor cell lines." (PMID 39997039, 2025). "In this study, we evaluate the use of clinically relevant non-ablative doses of radiation to guide and enhance the delivery of intravenously administered AMONs to brain tumor sites to silence MGMT and enhance the efficacy of CRT in orthotopic rat models of MGMT-positive human brain tumors." (PMID 33850305, 2022). "We provide hypothesis-generating data to support further evaluation of IV AMONs in combination with standard CRT regimes to enhance its efficacy in MGMT overexpressing brain tumors." (PMID 33850305, 2022). "Similarly predictive (more favourable) outcomes of MGMT gene silencing are seen in peadiatric brain tumours." (PMID 35582280, 2019). "The utility of biomarkers in managing brain tumors has grown in importance over the past decades, some being already used in daily medical practice, e.g. the methylation of the promoter of the gene for O6-methylguanine-DNA methyltransferase (MGMT)." (PMID 31142339, 2019). "The double-labelling-cocktail method may also be useful in the study of heterogeneity of MGMT expression in brain tumours." (PMID 24252243, 2013). "Indeed, MGMT expression was evaluated by semiquantitative scoring in the majority of the brain tumour studies (18 out of 20) and in 18 out of 32 systemic tumour series." (PMID 21269507, 2011). "Moreover, studies evaluating the tumor MGMT levels in patients with brain tumors receiving nitrosureas reported a positive correlation between low level content of MGMT and a better survival." (PMID 21067582, 2010). "Indeed, this hypothesis is further supported by results obtained from MTT assays performed in MGMT+ paediatric brain tumour cell lines." (PMID 35582280, 2019). "In addition to identifying mutations correlated with specific subclonal expansions, we also examined the expression of O6-methylguanine DNA methyltransferase (MGMT), which is known to drive brain tumor recurrence through increased expression in post-temozolomide lesions." (PMID 29440180, 2018). "Interestingly, selected biomarker status is progressively being considered in the clinical assessment and management of certain subtypes of brain tumors such as the evaluation of O6-methylguanine-DNA methyltransferase (MGMT) promoter methylation status in elderly patients diagnosed with a GBM." (PMID 26287251, 2015). "Similarly, brain tumors with MGMT protein show little responce to Temozolomide34." (PMID 25989388, 2015). "Moreover, regulation of MGMT expression in brain tumours seems to be a complex phenomenon in which abnormal methylation of the promoter region may not be the only determining factor." (PMID 21269507, 2011). "Chemical Exchange Saturation Transfer (CEST) MRI enables non-invasive detection of endogenous molecules for brain tumor grading and assessment of IDH and MGMT status." (PMID 40806525, 2025). "A total of 29 relevant brain tumor genes are indicated on the graph and notably PTEN and MGMT are located on chromosome 10 whereas SMARCB1 and NF2 are located on chromosome 22." (PMID 40136376, 2025). "In this work, we developed a sandwich DNA-immunosensor for quantification of the methylated tumour suppressor gene O-6-methylguanine-DNA methyltransferase (MGMT), which is a potential biomarker for brain tumours and breast cancer." (PMID 33921234, 2021).
brain tumors (continued). "Consequently, MGMT promoter methylation was proposed as a prognostic biomarker of the response of GBMs to TMZ, and quality assured MGMT testing was implemented as a molecular diagnostic method in the 2016 World Health Organization (WHO) classification of brain tumors." (PMID 34769368, 2021). "Based on these findings, we propose that the combination of H2AFJ levels with MGMT and/or IDH1 features is likely able to more precisely identify brain tumor patients who will have good outcomes after TMZ therapy." (PMID 31906036, 2019). "Considering the robust and reproducible nature of DNA methylation in the classification of brain tumors, this signature has great value in predicting the TMZ sensitivity of the GBMs that lack MGMT promoter methylation." (PMID 31611911, 2019). "More importantly, related to this study, our laboratory has demonstrated the ability of DSF and to inhibit O6-methylguanine DNA methyltransferase (MGMT), a DNA repair protein highly expressed in brain tumors." (PMID 29423059, 2018). "Depletion of MGMT activity by the selective inhibitor, O6-BG, reportedly enhanced the cytotoxicity of TMZ in human brain tumour and melanoma xenografts." (PMID 20924375, 2010). "Temozolomide (TMZ) is used to treat primary brain tumors and non-small cell lung cancer (NSCLC) brain metastases, yet therapeutic efficacy is often limited by the DNA repair enzyme O6-methylguanine-DNA methyltransferase (MGMT)." (PMID 41763308, 2026). "The stresses, albeit pleiotropic with the potential for affecting many redox regulatory processes and signaling, did trigger significant inhibition of MGMT in brain tumor cells in cell culture and xenograft settings; no toxicity on host tissues was observed." (PMID 39997039, 2025). "Using tissue microarrays of 158 brain tumour samples, we assessed CD3, CD4, CD8, CD20, CD138, Granzyme B (GzmB), 5-Lipoxygenase (5-LOX), Programmed Death-Ligand 1 (PD-L1), O-6-Methylguanine-DNA Methyltransferase (MGMT) and Transglutaminase 2 (TG2) expression by immunohistochemistry (IHC)." (PMID 38816839, 2024). "In brain tumor cell lines, DSF reduced MGMT activity in a rapid and dose-dependent manner." (PMID 36091753, 2022). "Since TNTs spread O-6-methylguanine-DNA methyltransferase (MGMT) protein and mRNA to other cells, they could also serve as anatomical structures contributing to brain tumor networks which will require further investigation." (PMID 36357661, 2022). "The results of the MS‐HRM analysis of all analyzed genes (SFRP1, SFRP2, RUNX3, CBLN4, INA, MGMT, and RASSF1A) showed that their promoter sequence methylation level is significantly higher (P < 0.0001) in DNA samples from brain tumor patients than in the non‐neoplastic brain sample." (PMID 32783304, 2020). "Although strong agreement between MSP and IHC has been previously reported, there is growing evidence that MGMT promoter methylation assessment through MSP does not correlate well with MGMT protein expression as detected by IHC in brain tumours." (PMID 21269507, 2011). "Although neither study used the more commonly used 7-day/14-day or 21-day/28-day regimens, nor was brain tumour specifically evaluated, both studies suggest that dose-intense temozolomide schedules can deplete MGMT activity in tumour." (PMID 20628383, 2010). "Therefore, there is an urgent need for novel, efficient, and non-toxic MGMT inhibitors, not only for brain tumors but also for other MGMT-proficient cancers." (PMID 39997039, 2025).
brain tumors (continued). "However, there is a major problem in interpretation of MGMT immunostaining in brain tumours due to the fact that normal non-tumourous elements within the tumour (including endothelial cells, lymphocytes and macrophages) normally express MGMT." (PMID 24252243, 2013). "Furthermore,we compared the cytotoxic effects of compound 1 on variouswild-type brain tumor cell lines, including U87MG, PT#3, LN229 GBMcells, and CT-2A mouse astrocyte cell line as well as TMZ-resistantvariants cell lines, including U87MG-R, PT#3-R, CT-2A-R, and T98G(MGMT-positive)." (PMID 39836457, 2025). "The post‐treatment recurrent brain tumors exhibited a decrease in expression of the mismatch repair (MMR) proteins, MSH6 and MLH1, but their methylated MGMT status did not changed." (PMID 26778701, 2016).
melanoma (79 papers, 1995 to 2026). A malignant, usually aggressive tumor composed of atypical, neoplastic melanocytes. "MGMT is a crucial gene in DNA repair pathways, and its loss is also associated with an increased risk of melanoma development." (PMID 27776349, 2017). "Only the gene body of MGMT showed a low level of methylation increase in CDKN2A-mutated patients compared to sporadic melanoma patients (2% increase in the methylation level, P = 0.02)." (PMID 26106605, 2015). "Acquired resistance to the chloroethylating antineoplastic agent fotemustine in melanoma cells is caused by reactivation of the DNA repair gene MGMT, which is associated with hypermethylation of the body of the gene." (PMID 14562026, 2003). "All melanoma patients with the MGMT 53/84 polymorphism except one had tumours with high MGMT expression." (PMID 14562026, 2003). "Polymorphisms in the coding region of the MGMT gene were also investigated in tumours from 52 melanoma patients by PCR/SSCP and nucleotide sequence analyses." (PMID 14562026, 2003). "The SNPs in the MGMT gene identified in these melanoma patients are heterozygous; thus the wild-type allele is always present." (PMID 14562026, 2003). "Single nucleotide polymorphisms in the coding regions of the MGMT gene, exons 2–5, were investigated in DNA extracts from melanoma metastases by PCR/SSCP and nucleotide sequencing." (PMID 14562026, 2003). "In our study, all except one of the melanoma patients with the 53/84 polymorphism in exon 3 had tumours with high MGMT expression." (PMID 14562026, 2003). "MGMT promoter methylation is also associated with the occurrence and invasion of melanoma." (PMID 32141507, 2020). "Moreover, the methylation status of MGMT, which encodes a repair protein by removing alkyl groups from the O6-position of guanine residues and its promoter, has been proposed as a biomarker in glioblastoma, colorectal cancer and melanoma." (PMID 29100458, 2017). "Thus, we planned this study in MM patients to verify the hypothesis that depletion of MGMT induced by low dose TMZ could render melanoma cells more susceptible to FM." (PMID 21067582, 2010). "These polymorphisms identified in our melanoma patients may affect MGMT function differently." (PMID 14562026, 2003). "Within the scope of our investigation, we explored signalling pathways that regulate MGMT expression in melanoma cells and found that TMZ stimulation promoted p‐ERK1/2 protein expression and increased MGMT promoter transcriptional activity." (PMID 39873425, 2025). "TMZ‐promoted MGMT transcription contributed to instinctive chemoresistance by activating the ERK signalling pathway in malignant melanoma." (PMID 39873425, 2025). "Studies conducted in vitro, wherein melanoma cells transfected with MGMT were incubated with various alkylating agents including melphalan, chlorambucil, busulfan, and thiotepa, demonstrated no discernible difference in cell survival post-treatment." (PMID 39055560, 2024). "In this study, we evaluated the effects of in vitro molecular biological regulation of MGMT in GBM, GSC, and melanoma cell lines and found that MGMT expression differentially regulates the radioresponse of these tumors." (PMID 38811596, 2024). "Phase II clinical trials assessing lomeguatrib in patients with melanoma have demonstrated that lomeguatrib reduces MGMT activity and potentiates the efficacy of temozolomide." (PMID 39055560, 2024). "Specifically, in MGMT-positive melanoma cells, the antiproliferative impact of temozolomide is substantially augmented when used in conjunction with PARPi, compared to the administration of temozolomide as a monotherapy." (PMID 39055560, 2024). "High expression levels of MGMT in advanced melanoma patients correlate with resistance to DTIC and poor survival." (PMID 37024907, 2023). "Our study demonstrated that the bioactive compound, Protocatechuic aldehyde, synergistically promoted the cytotoxicity of DTIC to melanoma cells through the destabilization of MGMT protein." (PMID 37024907, 2023).